USP1 (ubiquitin specific peptidase 1)
Diseases named in the same sentence as USP1 in open-access papers (continued):
Sharing a sentence is not in itself a finding about the gene and the disease.
lung carcinoma (11 papers, 2013 to 2023). "Expression of USP1 was significantly correlated with expression of Oct4 and Sox2 in human lung cancers, in keeping with previous reports." (PMID 32549341, 2020). "Furthermore, USP1-knockout A549 lung cancer cells were generated to validate the deubiquitinating activity of USP1 on MAST1 abundance." (PMID 35966591, 2022). "The deubiquitylating enzyme USP1 plays an important role in tumor progression; high USP1 expression has been reported in various tumors, and USP1 inhibition inhibits tumor cell growth in various cancers including lung cancer." (PMID 36357365, 2022). "Furthermore, blocking USP1 inhibited DNA repair and induced apoptosis in multiple myeloma cells and sensitized lung cancer cells to cisplatin." (PMID 31921663, 2019). "Interestingly, this can be reversed by two closely-related Usp12 family members, Usp46 in colon cancer and Usp1 in lung cancer which both deubiquitinate and stabilise PHLPP." (PMID 25216524, 2014). "Interestingly, inhibition of Usp1, a close homologue of Usp12 has been shown to have promising results in lung cancer systems which was achieved by inhibiting the Usp1-Uaf-1 complex." (PMID 25216524, 2014). "Current data on USP1 expression in lung cancer are somewhat controversial." (PMID 23937906, 2013). "Interestingly, the expression of USP1 was significantly increased in a number of cancers, and blocking USP1 inhibited DNA repair, induced apoptosis in multiple myeloma cells, and sensitized lung cancer cells to cisplatin." (PMID 31921663, 2019). "In lung cancer, integrin β4/PXN/FAK complex mediates cisplatin resistance through regulating ubiquitin specific peptidase 1 (USP1) and voltage-dependent anion channel 1 (VDAC1), which are associated with mitochondrial function and maintaining genomic stability." (PMID 37770930, 2023). "USP1 overexpression (Fold change > 1.5; P-value < 0.05) was reported in 25% (4/16) of the lung cancer microarray sets available through Oncomine, whereas none of these studies reported significant downregulation of USP1." (PMID 23937906, 2013).
prostate carcinoma (9 papers, 2011 to 2026). A carcinoma that arises from epithelial cells of the prostate gland. "Both in vitro and in xenograft mouse models suggested that inhibition of USP1 suppressed tumor growth and reduced the drug resistance of prostate cancer cells." (PMID 41541703, 2026). "USP1 enhances the stability of CCAAT/enhancer-binding protein β (C/EBPβ) and accelerates lipid formation and lipid accumulation in prostate cancer." (PMID 39944823, 2025).
colorectal cancer (8 papers, 2019 to 2025). A primary or metastatic malignant neoplasm that affects the colon or rectum. "In fact, commercially available USP1 inhibitors have shown efficacy in models of prostate, breast and colorectal cancer." (PMID 36240066, 2022). "In order to examine the expression of USP1, we first performed the detection in colorectal cancer tissues and the paired normal tissues through online dataset, western blot, qRT-PCR, and immunohistochemical staining analysis." (PMID 32742193, 2020). "In this study, Ubiquitin specific protease 1 (USP1) expression was found significantly increased in some colorectal cancers (CRC)." (PMID 31921663, 2019). "Moreover, blocking USP1 can inhibit DNA damage repair in osteosarcoma and colorectal cancer cells, trigger tumor cell apoptosis, and enhance the sensitivity to chemotherapeutic drugs." (PMID 36357365, 2022). "Furthermore, inhibition of USP1 increased the sensitivity of colorectal cancer cells to DNA-damaging chemotherapeutic agents." (PMID 35923700, 2022).
glioblastoma (8 papers, 2019 to 2025). The most malignant astrocytic tumor (WHO grade IV). "Pimozide, an USP1 inhibitor, is in clinical trial for glioblastoma." (PMID 33800394, 2021). "Regarding DUBs, pimozide, a USP1 inhibitor, has shown the ability to reduce glioblastoma (GBM) growth in xenograft models and has entered Phase I/II clinical trials for GBM." (PMID 40296903, 2025). "A similar ‘bind-unfold-lock’ mechanism was proposed for USP1 translational regulation by hnRNP H/F and DHX36 in glioblastoma or for the CNBP-targeted mRNAs." (PMID 36107769, 2022).
glioma (8 papers, 2017 to 2025). A benign or malignant brain and spinal cord tumor that arises from glial cells (astrocytes, oligodendrocytes, ependymal cells). "Among the selected DUBs significantly linked to the DNA damage repair pathway, the glioma and MB datasets shared several DUBs, including USP1, USP47, UCHL5, and OTUD1, which cover five major DNA damage repair pathways (BER, NER, FA, TLS, DSB)." (PMID 37892185, 2023). "Overall, the H3.3K27M mutation in high-grade glioma is a potential biomarker for poor prognosis mainly due to the infiltration of glioma cells that is at least partially mediated by the β-catenin/USP1/EZH2 pathway." (PMID 36230759, 2022). "E2F1 has been reported to be upregulated by PDGF in gliomas and supports pro-neural glioma progression by enhancing USP1 expression." (PMID 37283490, 2023). "Based on these results, H3.3K27M promotes glioma cell invasion and migration through the β-catenin/USP1 signaling pathway." (PMID 36230759, 2022). "Taken together, these results indicate that H3.3K27M plays an important role in promoting glioma cell migration and invasion by activating the ꞵ-catenin/USP1/EZH2 signaling pathway." (PMID 36230759, 2022). "In the current study, the circ‐USP1 expressing level was up‐regulated in glioma cerebral microvascular endothelial cells (GECs) of the BTB model in vitro." (PMID 31654502, 2020). "USP1 in glioma, as well as USP7 and USP34, also converge on EZH2 to promote tumorigenesiss." (PMID 37892185, 2023). "Furthermore, we demonstrated that the upregulation of USP1 was attributed to the activation of β-catenin, a classic signal transduction protein related to the malignant progression of glioma, in our study." (PMID 36230759, 2022). "Finally, to investigate the potential clinical importance of our findings, we analyzed the expression of hnRNP H/F, DHX36 and USP1 in human glioma patient tissues." (PMID 32461552, 2020). "Circ‐USP1 is significantly up‐regulated in our microarray screen detected by comparing human cerebral microvascular endothelial cell line (ECs) with endothelia cells co‐cultured with glioma (GECs)." (PMID 31654502, 2020). "The β-catenin/USP1 pathway may be a potential target in H3.3K27M mutant glioma." (PMID 36230759, 2022). "Single or combined treatment of circ‐USP1 and miR‐194‐5p effectively promoted anti‐tumour drug doxorubicin across BTB to induce apoptosis of glioma cells." (PMID 31654502, 2020). "USP1-mediated stabilization of EZH2 promotes the occurrence and development of glioma." (PMID 36230759, 2022). "We revealed that silencing circ‐USP1 could increase the BTB permeability via miR‐194‐5p/FLI1‐mediated regulation, which would provide a new therapeutic strategy of glioma." (PMID 31654502, 2020). "Nevertheless, β-catenin/USP1/EZH2 has no obvious effect on the proliferation of glioma cells." (PMID 36230759, 2022). "Overall, this present study identified the crucial regulation of circ‐USP1 on BTB permeability via miR‐194‐5p/FLI1 axis‐mediated regulation of tight junction proteins, which might facilitate the development of therapeutics against human gliomas." (PMID 31654502, 2020). "In order to clarify whether the treatment of circ‐USP1 and miR‐194‐5p alone or in combination could increase the BTB permeability and promote the anti‐tumour drug doxorubicin (DOX) delivery across BTB to induce the apoptosis of U87 glioma cells." (PMID 31654502, 2020).
leukemia (6 papers, 2018 to 2024). A malignant (clonal) hematologic disorder, involving hematopoietic stem cells and characterized by the presence of primitive or atypical myeloid or lymphoid cells in the bone marrow and the blood. "Interestingly, USP1 inhibitors have shown promise in leukemia treatment." (PMID 38534787, 2024). "Mistry and colleagues have demonstrated that newly developed small-molecule inhibitors of USP1 lead to the breakdown of ID1 and are harmful to leukemia cells." (PMID 39048945, 2024). "USP1 mRNA over-expressed in melanoma, gastric, cervical and NSCLC; under-expressed in leukaemia and lymphoma." (PMID 31287417, 2019).
liver cancer (6 papers, 2020 to 2025). An epithelial or non-epithelial malignant neoplasm that arises from the liver. "In conclusion, USP1, as a novel diagnostic and predictive marker in the treatment of liver cancer, can provide new ideas for the development of targeted drugs for liver cancer treatment." (PMID 35875077, 2022). "In liver cancer, USP1 can maintain the survival of hepatic circulating tumor cells by deubiquitinating and stabilizing TBL1 protein." (PMID 35875077, 2022). "Studies have shown that USP1 can promote the stability of RPS16 protein and promote the proliferation and migration of liver cancer cells by binding to the cys90 (C90) site at the N-terminus of UAF1 (a cofactor of USP1)." (PMID 35875077, 2022). "Our current research showed that USP1 promotes the growth and migration of liver cancer cells by maintaining the stability of RPS16 protein." (PMID 34154657, 2021). "After data mining in the Oncomine database, we found that the mRNA expression of USP1 was elevated in various types of cancers (cancer vs normal), such as liver cancer, sarcoma and bladder cancer." (PMID 32951278, 2020). "In liver cancer, USP1 is thought to play a key role in the immune infiltration process of tumors." (PMID 35875077, 2022). "However, to our knowledge, few studies have investigated the role of USP1 in liver cancer." (PMID 32951278, 2020). "Consistent with the analysis of the TCGA database, the protein expressions of USP1 and RPS16 in liver cancer tissues are up-regulated compared with adjacent liver tissues." (PMID 34154657, 2021).
viral infection (6 papers, 2017 to 2026). "Among the USP members, USP1 functions as a viral infection-induced physiological enhancer of TBK1 expression when bound to USP1 the K48-linked polyubiquitination of TBK1, resulting in enhanced TLR3/4 and RIG-I-induced IRF3 activation and IFNβ secretion." (PMID 34707613, 2021). "To confirm that deubiquitination of PCNA and FANCD2 was mediated through USP1 in virus infection, we depleted USP1 using siRNA knockdown." (PMID 41533576, 2026). "UAF1 and the USP1/UAF1 complex are also important in viral infection and pathogenesis, particularly in viral genomic integration and replication." (PMID 29091922, 2017). "While there have been many advances in our understanding of the role of USP1 in the regulation of DNA damage repair and chromosome stability, including the development of an inhibitor, other aspects of USP1 function, including its participation in viral infection and pathogenesis, remain elusive." (PMID 29091922, 2017). "Several studies have reported an interaction between the PDZ domain of MAST kinases and proteins such as USP1, SNTB2, PTEN, RABV-G, NHE3, and ACE2, which are involved in diverse processes like longevity, neurite outgrowth, and viral infection." (PMID 41237908, 2025). "Importantly, inhibition of USP1 with C527 in UL138-mutant virus infection does not further impact virus replication." (PMID 41533576, 2026). "The results showed that the RIG-I protein expression level was significantly elevated after viral infection in LV-USP1 cells, but significantly decreased in sh-usp1 cells, however, there was no significant change in the protein level expression of RIG-I after MG132 treatment." (PMID 40369332, 2025).
lymphoma (5 papers, 2019 to 2024). A malignant (clonal) proliferation of B- lymphocytes or T- lymphocytes which involves the lymph nodes, bone marrow and/or extranodal sites. "Therefore, loss of USP1 in the Eμ-Myc/c-Rel−/− lymphomas might act as signalling pathway switch where CHK1 protein is lost concomitant with PI3K/AKT activity being up-regulated." (PMID 36240067, 2022). "Eμ-Myc/cRel−/− lymphomas have downregulated the expression of USP1 and checkpoint kinase 1 (CHK1) protein that results in resistance to treatment by specific CHK1i." (PMID 39664521, 2024). "We demonstrate that treating WT Eμ-Myc lymphoma cells with the USP1 inhibitor ML323 was highly effective at reducing tumour burden in vivo." (PMID 36240066, 2022). "For example, we have identified down-regulation of USP1 mRNA and protein in the Eμ-Myc/c-Rel−/− lymphomas." (PMID 36240067, 2022). "Here, given our data and a previous report that USP1 acts as a CHK1 DUB, we demonstrated that inhibition of USP1 using ML323 effectively killed wild-type Eμ-Myc lymphoma cells." (PMID 36240066, 2022). "Nevertheless, the target of USP1 in hematological malignancies including lymphoma, was not determined." (PMID 36352191, 2023). "However, key components of the work from Eμ-Myc lymphomas, such as down-regulation of CHK1 and USP1 protein, were also seen in independently derived populations of CCT244747 resistant U2OS cells, and SRA-737 resistant Huh-7 cells." (PMID 36240066, 2022).
B-cell lymphoma (4 papers, 2023 to 2025). "Although ubiquitin-specific protease 1 (USP1) plays a key role in cancer, the carcinogenic effect of USP1 in B-cell lymphoma remains elusive." (PMID 36352191, 2023).
cholangiocarcinoma (4 papers, 2022 to 2025). A carcinoma that arises from the intrahepatic biliary tree (intrahepatic cholangiocarcinoma) or from the junction, or adjacent to the junction, of the right and left hepatic ducts (hilar cholangiocarcinoma). "In summary, this study is the first to elucidate the tumor-promoting role of the USP1–PARP1 axis in cholangiocarcinoma, filling a critical gap in the understanding of USP1 in this malignancy." (PMID 41301681, 2025). "Despite its involvement in various cancers, the function of the deubiquitinase USP1 (ubiquitin-specific protease 1) is unexplored in cholangiocarcinoma (CCA)." (PMID 37821462, 2023). "This study shows that USP1 stabilizes PARP1 via K197 deubiquitination, fueling cholangiocarcinoma growth and metastasis." (PMID 41301681, 2025). "This review synthesizes current knowledge on six USP members—USP1, USP3, USP8, USP9X, USP21, and USP22—and delineates their context-dependent roles across cholangiocarcinoma and GBC subtypes." (PMID 41301681, 2025). "Moreover, USP1 is upregulated in cholangiocarcinoma (CCA) and its positive regulation of PARP1 leads to increased proliferation, invasion, and metastasis in CCA models." (PMID 37821462, 2023).
melanoma (4 papers, 2018 to 2025). A malignant, usually aggressive tumor composed of atypical, neoplastic melanocytes. "USP1 overexpression has been reported in many cancer types, like sarcoma and melanoma." (PMID 35663242, 2022).
multiple myeloma (4 papers, 2019 to 2023). "Inhibition of USP1 has been shown to reduce myeloma cell viability, inhibit the growth of multiple myeloma cells and overcome bortezomib resistance." (PMID 37048102, 2023). "In the context of multiple myeloma, the expression of the HNRNPA2B1, USP1, RRM1, SPAG5, PCNA and TOP2A genes has been studied." (PMID 37048102, 2023).
anemia (3 papers, 2012 to 2025). A reduction in the number of red blood cells, the amount of hemoglobin, and/or the volume of packed red blood cells. "In human cells Usp1 deubiquitylates PCNA as well as the Fanconi's anaemia protein FANCD2." (PMID 22829782, 2012).
bladder cancer (3 papers, 2020 to 2025). "We used USP1-overexpressing T24 and USP1-deficient UMUC3 bladder cancer cell lines to ascertain the role of USP1 in bladder tumor development." (PMID 39513905, 2024). "In summary, we found that USP1 expression was upregulated and associated with a poor prognosis in bladder cancer." (PMID 39513905, 2024). "As a deubiquitination enzyme, ubiquitin-specific protease 1 (USP1) is associated with tumor progression; however, its role in bladder cancer is unknown." (PMID 39513905, 2024). "Ubiquitin-specific protease 1 (USP1) has been found to be upregulated in human bladder cancer cells and to correlate with poor patient prognosis." (PMID 41228251, 2025). "We performed cell proliferation, colony formation, and Transwell assays to determine the effect of USP1 on bladder cancer cells." (PMID 39513905, 2024). "To explore the mechanism of action of USP1 in bladder cancer cells, we performed RNA-seq analysis using wild-type and USP1-knockout UMUC3 cells." (PMID 39513905, 2024). "Recently, several studies have indicated that USP1 plays an important role in tumor development; however, the effect of USP1 on bladder cancer remains to be determined." (PMID 39513905, 2024). "Next, we analyzed overall survival using the web server GEPIA and found that bladder cancer patients with higher USP1 expression had poorer survival than those with low USP1 expression." (PMID 39513905, 2024). "Here, we performed RNA-seq analysis and luciferase pathway screening to explore the mechanism of USP1 in bladder cancer." (PMID 39513905, 2024). "We then examined USP1 protein levels in bladder cancer using a tissue microarray with bladder tissues via immunohistochemistry." (PMID 39513905, 2024). "We found that USP1 overexpression promoted the proliferation and migration of T24 bladder cancer cells." (PMID 39513905, 2024). "In this study, we analyzed USP1 expression in the online datasets, which showed that USP1 was upregulated in bladder cancer." (PMID 39513905, 2024). "To explore USP1’s function in bladder cancer, we constructed USP1-knockout cell lines in UMUC3 cells." (PMID 39513905, 2024). "All the results suggested that USP1 is an oncogene in bladder cancer, which promotes cancer progression by targeting c-MYC." (PMID 39513905, 2024). "We found that USP1 expression in T24 bladder cancer cells was lower than that in UMUC3 bladder cancer cells." (PMID 39513905, 2024). "These two cell lines represent distinct stages of bladder cancer, which may suggest that USP1 may have an effect on different stages of bladder cancer." (PMID 39513905, 2024). "All the results showed that USP1 is closely related to bladder cancer." (PMID 39513905, 2024). "Our study revealed a new carcinogenic mechanism of action of USP1, which may be a potential therapeutic target for bladder cancer." (PMID 39513905, 2024). "A xenograft mouse model was used to study the role of USP1 in bladder cancer." (PMID 39513905, 2024). "The results showed that USP1 expression was upregulated in the bladder cancer samples." (PMID 39513905, 2024). "Further studies are required to determine whether treatment with USP1-specific inhibitors can inhibit bladder cancer development and progression." (PMID 39513905, 2024). "This study aimed to analyze USP1 expression and study its roles in bladder cancer." (PMID 39513905, 2024). "Moreover, a high level of USP1 expression in bladder cancer was correlated with poor prognosis." (PMID 39513905, 2024). "Finally, we revealed a novel mechanism of USP1 in bladder cancer development and progression." (PMID 39513905, 2024). "Our research suggested that USP1 may be a potential target for bladder cancer treatment." (PMID 39513905, 2024). "Next, we explored the mechanisms and found that USP1 bound to and stabilized c-MYC by mediating its deubiquitination, thereby promoting the progression of bladder cancer." (PMID 39513905, 2024).
bladder cancer (continued). "However, the effect and molecular mechanisms of USP1 in bladder cancer have not been reported." (PMID 39513905, 2024).
colon cancer (3 papers, 2022 to 2026). "USP32, USP1, USP37, USP12, and USP6 are elevated in macrophages, while USP32, USP9X, USP46, USP12, USP36, and USP24 are upregulated in classical monocytes of colon cancer relative to the control group." (PMID 41356798, 2026).